LDHA (lactate dehydrogenase A)
Diseases named in the same sentence as LDHA in open-access papers (continued):
Sharing a sentence is not in itself a finding about the gene and the disease.
cancer (continued). "The β-catenin-mediated activation of glycolytic proteins leads to the activation of c-Myc, and, consequently, c-Myc upregulates the band level of PKM2, LDHA, and HK2 in cancer cells." (PMID 39273365, 2024). "By analyzing human tissue sample data from the Cancer Cell Line Encyclopedia (CCLE) and Genotype-Tissue Expression (GTEx) sources, we found that LDHA is highly expressed in many cancers as compared with normal tissues." (PMID 39225102, 2024). "Our study demonstrates that LDHA facilitates glycolysis by promoting the NADH/NAD+ cycle, highlighting its critical role in ensuring efficient energy production in cancer cells." (PMID 39680520, 2024). "The β-catenin-mediated activation of glycolytic proteins promotes the oncogenic potential of c-Myc, since c-Myc upregulates the band level of HK2, LDHA, and PKM2 in cancer cells." (PMID 39273365, 2024). "In cancer cells, deregulated LDHA facilitates the regeneration of NADH into NAD+ and boosts metabolic flux through the pentose phosphate pathway, and hence fuelling cancer cell growth by providing essential metabolic substrates." (PMID 39021353, 2024). "To assess the impact of LDHA CNV on patient survival, we categorized patients into amplification and deletion groups in five cancer types that had sufficient sample sizes." (PMID 38198170, 2024). "Of note, the upregulation of MACC1 expression can also be detected in trastuzumab-resistant cancer cells, where it induced the core enzymes of glycolysis hexokinase‐2 (HK2) and lactate dehydrogenase A (LDHA) through PI3K/Akt." (PMID 39580452, 2024). "Numerous studies have confirmed the upregulation of LDHA expression in cancer cells, whereas the expression level of LDHB remains relatively unchanged in cancer cells and normal tissues." (PMID 38731521, 2024). "Another five targetable gene dependencies had clinical inhibitors that have reached at least a phase II trial (BIRC2, ITGB1, MAP3K11, LDHA and PTPN1), with 3 having been applied to other cancer types (BIRC2, ITGB1, and LDHA)." (PMID 37997254, 2024). "Lactate dehydrogenase A (LDHA) and LDHB are lactate dehydrogenase tetrameric enzymes utilized by cancer cells to produce lactate from pyruvate." (PMID 38956544, 2024). "The high LDHA expression group exhibited decreased numbers of CD8+ cells and CD11c+ cells, suggesting that increased glycolysis in cancer cells exerted an immunosuppressive effect on the TME." (PMID 39343933, 2024). "Central carbon metabolism in cancer-related genes, i.e., SLC16A3, FGFR3, LDHA, PGAM1, and SLC2A1, significantly reduced after treatment with CTPPPPD." (PMID 39275122, 2024). "Therefore, the AKT pathway may be a downstream effector related to LDHA in cancer." (PMID 39680520, 2024). "Notably, using LDHA inhibitors to treat cancer may present certain obstacles." (PMID 38983918, 2024). "Therefore, considering the pivotal role played by LDHA in cancer growth, angiogenesis, metastasis, and drug resistance (e.g., tamoxifen resistance), it was assumed that LDH could be an extremely attractive target for the development of small molecules as anticancer agents." (PMID 38731601, 2024). "They found that glycolysis-related genes, including lactate dehydrogenase A (LDHA) and enolase 2 (ENO2) expression profiles significantly changed between fibroblasts cocultured with highly metastatic cancer cells and low metastatic potential cancer cells." (PMID 38562556, 2024). "In the current study, we use a well-established murine model of SCC coupled with genetic deletion of LDHA and GLS to test the limits of cancer metabolic flexibility." (PMID 39303037, 2024). "The European prospective investigation into cancer and nutrition (EPIC) array was used to analyze the correlation between immune cells and LDHA in the TCGA dataset." (PMID 38567154, 2024). "After further transformation into cancer, OIP5-AS1 sponges miR-323a, leads to an increase in LDHA and thus reprogram the metabolism of pyruvate into lactic acid." (PMID 38773399, 2024).
cancer (continued). "This coupling mainly depends on lactate dehydrogenase A (LDH‐A), which is overexpressed in different types of cancers, and therefore represents an appealing therapeutic target." (PMID 39276013, 2024). "To investigate the impact of LDHA copy number variation (CNV) on patient prognosis, we performed CNV and survival analyses across twenty-four different cancer types using data from the TCGA project." (PMID 38198170, 2024). "But in these cancers, survival analysis of CNV and expression level indicated LDHA cannot be utilized for prognostic prediction." (PMID 38198170, 2024). "Based on the TCGA data, we checked the transcript expression level of isoenzymes which are important for cancer cells, i.e., PFKM, PKM2, and LDHA, among HNSCC patients." (PMID 38132445, 2023). "In 4T1.2-EV lysate, LDHA and MCT4 were detected as similar sized bands as in 4T1.2 cancer cell lysate." (PMID 38033489, 2023). "Mechanically, APOL3 can promote ubiquitylation-related degradation of LDHA, APOL3-LDHA axis inhibits cancer cell proliferation, promote ferroptosis and CD8+ T cells' antitumor ability." (PMID 36923931, 2023). "The increased production of lactate from pyruvate, which is typical for cancer cells, is gathered by the elevated LDH enzymes (LDHA, LDHB)." (PMID 37175655, 2023). "The overexpression of glycolytic-involved genes (including LDHA, HK, GLUT1 or PKM2) has been shown in 24 types of cancer, including more than 70% of the total amount of human cancer cases." (PMID 37345199, 2023). "Lactate dehydrogenase A (LDH-A) is a transcriptional target of the oncogene c-MYC and is involved in the upregulation of glycolysis in cancer cells that rely on Warburg metabolism." (PMID 37765194, 2023). "Among them, Y10 phosphorylation of LDHA by intracellular kinase FGFR1 enhanced LDHA activity and provided pro-metastatic advantage to cancer cells." (PMID 37480145, 2023). "This included ERα, the transcriptional repressor protein E2F-4, the microtubule protein αTubulin and proteins involved in cancer cell metabolism (GLUT1, LDHA and PDK1-pSer241) and stress responses (eIF2A-pSer51)." (PMID 37596623, 2023). "HIF‐1 can enhance glycolysis in cancer cells by upregulating the expression of GLUT1 and LDHA in breast cancer cells." (PMID 36994237, 2023). "Many metabolic enzymes have been studied as targets for cancer treatment, such as GLUT1 inhibitor STF-31, HK2 inhibitor phenylnitrobenzylhydrazine, LDHA inhibitor NCI-006D, etc 20-22." (PMID 37670970, 2023). "Proteins such as glucose transporter 1 (GLUT1), lactate dehydrogenase A (LDHA), and monocarboxylate transporter 4 (MCT4) are central to the metabolic reprogramming seen in cancer cells, marking them as significant players in CRC pathophysiology." (PMID 37760801, 2023). "Human lactate dehydrogenase A (LDHA) is competitively inhibited by oxaloacetate (OAA), which prevents LDHA from functioning in cancer cells." (PMID 38106701, 2023). "Here, we demonstrate that the inhibition of LDHA and GLS1—two metabolic targets that are currently under investigations in clinical trials for cancer therapy—impairs anti-CD40 monoclonal antibody-induced antitumor responses." (PMID 36823405, 2023). "One key element in aerobic glycolysis or the Warburg effect is lactate dehydrogenase A (LDHA), which regenerates the electron acceptor NAD+ and is widely considered an appealing target for cancer therapeutics." (PMID 38136270, 2023). "This is observed in many cancer types, including CRC, and is primarily driven by lactate dehydrogenase (LDH) composed of two subunits, LDHA and LDHB, and monocarboxylate transporters (MCTs)." (PMID 37816733, 2023). "OAA is a competitive inhibitor of LDHA, high pyruvate kinase M2 (PKM2) activity reduces LDHA activity via upregulating cytosolic OAA in cancer cells, the elevated PKM2 increase the de novo synthesis of OA and inhibit LDHA in cancer cells." (PMID 36778129, 2023).
cancer (continued). "Our findings reveal that the levels of mRNA and protein of LDHA, an important enzyme for lactic acid fermentation, tended to decrease after ARV-infected cancer cell lines." (PMID 36851737, 2023). "LDHA, ALDH3B1, and ALDH3A1 are all connected to the genesis and development of various cancers and play a role in mitochondrial energy metabolism." (PMID 36814901, 2023). "The nuclear translocation of LDHA has been significantly enhanced by ROS accumulation, and LDHA plays a role in modulating BCAA metabolism in cancer cells." (PMID 37298317, 2023). "Targeting the LDHA isozyme or total LDH has been previously reported to dysregulate the cell cycle, dampen the DNA damage response and induce apoptosis in numerous cancer cell lines." (PMID 34050611, 2022). "There are a couple of key enzymes and transporters regulating cancer cells glycolysis, such as GLUT1, PKM2, pyruvate dehydrogenase kinase isoform 2 (PDK2), and Lactate dehydrogenase A (LDHA)." (PMID 35978828, 2022). "The lactate dehydrogenase-A (LDHA) enzyme is found to play an essential role in the survival and proliferation of cancer cells." (PMID 36505423, 2022). "In cancer carbon metabolism pathways, the Warburg effect obviously appeared in HSCC; glycolysis-related gene HK, PKM, and LDHA were upregulated; and transporter genes GLS, SLC1A5, MCT4 and GLUT1 were upregulated." (PMID 36090994, 2022). "LDHA and LDHB are highly expressed in cancers, with LDHA responsible for converting pyruvate to lactate and LDHB responsible for converting lactate to pyruvate." (PMID 36230492, 2022). "LDH isoenzymes enriched in the LDHA subunit, such as LD5 and LD4, are thought to play an important role in maintaining glycolysis after bypassing the “Pasteur effect” in cancer cells." (PMID 36555705, 2022). "In this report, we confirmed that the effect of upstream kinases in facilitating LDHA Y10 phosphorylation is specific to FGFR1, indicating that the tyrosine kinase responsible for LDHA Y10 phosphorylation is cancer cell-type specific." (PMID 35525866, 2022). "Especially, the roles of hexokinase 2 (HK2), lactate dehydrogenase A (LDHA), and pyruvate dehydrogenase kinase 1 (PDK1) have been extensively studied in various cancers." (PMID 35403278, 2022). "Therefore, LDHA may serve as a potential target for cancer diagnosis and treatment." (PMID 36297369, 2022). "NHI-Glc-2, a novel inhibitor, dual-targets LDHA and GLUT-1 and makes anti-cancer effects more pronounced in combination with GEM." (PMID 36699061, 2022). "These include: CDH1, MUC1, THBS4, and MSLN for PEs related to cancer; ADA2, CXCL10, and WARS for TB-PEs; CRP, S100A9, and VIM for parapneumonic PEs; and C9, LDHA, HPX, LDHB, and C3 for benign-PEs." (PMID 35197508, 2022). "In this model, acetylation decreases the LDHA protein level and further affects the TCA cycle and oxidative phosphorylation for efficient energy production in cancer cells." (PMID 36407005, 2022). "It has been reported that LDHA is upregulated by both HIF-1alpha and Myc in cancer cells to promote lactate production." (PMID 35359405, 2022). "The Warburg effect was mainly reported in cancer, resulting in significant attention on LDH in cancer therapy, especially how different LDHA inhibiting methods show a positive effect." (PMID 36407005, 2022). "The results showed that the expression levels of LDHA, CS, IDH3G were significantly higher in cancer tissues than those in normal tissues." (PMID 36229828, 2022). "We mainly found that circ-CSNK1G1 acted as a cancer-driver to promote cell proliferation, migration, invasion and glycolysis energy metabolism in TNBC through the miR-28-5p/LDHA pathway." (PMID 36109751, 2022). "LDHA inhibitors FX11 and oxamate were found to reduce lactate production and retard the growth of cancer cells." (PMID 36497226, 2022).
cancer (continued). "HIF-1α guides the shift of glucose metabolism by promoting the expression of glycolytic enzymes and LDHA, which replenishes NAD+ for further metabolism in cancer cells, resulting in the state of aerobic glycolysis." (PMID 36407005, 2022). "As the major flavanol in green tea, (-)-epigallocatechin gallate inhibits LDHA in MIA PaCa-2 pancreatic cancer cells and confers the anti-cancer activity by disrupting the cellular metabolic network." (PMID 36247675, 2022). "LDHA also acts as a direct target of HIF-1α and c-MYC, contributing to biosynthesis and glycolysis to ensure fuel supply for energy and anabolism in cancer cells." (PMID 36699061, 2022). "Diverse inhibitors of LDHA, such as FX-11, AZ-33, and NHI-2, alter cancer cell survival through ROS accumulation, and knockdown of LDHA approaches similar effects." (PMID 36407005, 2022). "The majority of the proteins downregulated by miR-423-5p are involved in the pentose phosphate pathway, glycolysis, and carbon metabolism in cancer (G6PH and LDHA), as well as the biosynthesis of amino acids (SHMT2 and ASNS)." (PMID 36614061, 2022). "The corresponding heatmap analysis also indicated a positive correlation between P4HA1 and these five genes (BNIP3L, FUT11, LDHA, PGK1, and RPL17P50) in the majority of 32 types of cancers." (PMID 35812752, 2022). "LDHA is a promising target for cancer therapy, whereas LDHB is necessary for basal autophagy and cancer cell proliferation in oxidative and glycolytic cancer cells." (PMID 34725423, 2021). "Abnormally stimulated HIF-1 functioning as a transcription factor inhibits mitochondrial activity and promotes glycolysis and cancer cell growth by facilitating the expression of glycolysis transporters and key enzymes such as GLUT1, HK2, FBP, PKM2, and LDHA." (PMID 34540667, 2021). "C-Myc stimulates the anabolism of cancer cells by directly modulates the expression of several glycolysis genes, such as GLUT1, PKM2, and LDHA." (PMID 33748130, 2021). "The pyruvate analog Oxa, the LDHA/B/C inhibitor GNE, glucose deprivation and a LDHA/B double knockout inhibit LDH activity and thereby impair the radiosensitivity of cancer cells by an interference with the stress response." (PMID 34359663, 2021). "In cancer cells, GLUT1, HK2, PKM2, LDHA, MCT4, and other glycolysis-related proteins directly affect the glycolytic process." (PMID 33356727, 2021). "Otherwise, sodium oxamate, an inhibitor of lactate dehydrogenase A (LDHA1), induces cell death in several cancers." (PMID 33572255, 2021). "Studies have shown that MYC facilitates the anabolism of cancer cells by modulating the expression of multiple metabolic enzyme genes, such as GLUT1, PKM2, and LDHA." (PMID 33889549, 2021). "Nuclear PKM2 binding to Oct4 can upregulate cancer stemness-related genes (CD133, CD44, LDHA, NANOG), thus promoting the CSCs population’s enrichment from several human cancer types." (PMID 33828530, 2021). "In addition, LDHA controls a most potent pathway of rapid ATP production in cancer cells and its blockage deprives cancer cells from a major energy pathway, which may shift cell metabolism from glycolysis to mitochondrial oxidative phosphorylation (OXPHOS) and generate more ROS." (PMID 33902615, 2021). "Targeting of lactate dehydrogenase A (LDHA) and related metabolic pathways offers efficacious strategies for cancer cell treatment." (PMID 34740322, 2021). "In this study, we report that ETV4 is a critical transcription factor for metabolic rewiring in cancer cells, it promotes the transcription of hexokinase 2 (HK2) and lactate dehydrogenase A (LDHA), two enzymes indispensable for efficient glycolytic flux." (PMID 34052833, 2021). "Following irradiation, the decreased expression levels of LDHA and LDHB in the FaDu cancer cells and the HMC3 microglial cells corresponded to the decreased pyruvate-to-lactate flux on DNP 13C-MRI." (PMID 34436459, 2021).
cancer (continued). "In many aggressive cancers, the LDH-5 isoform is upregulated, probably as a consequence of the transactivation of the LDHA promoter by transcription factors responsible for the metabolic rewiring of their cells, such as c-myc and HIF-1α." (PMID 33804985, 2021). "Lactate dehydrogenase A (LDHA) reduces pyruvate to lactate and, at the same time, oxidizes NADH to NAD+, thus explaining the low levels of cancer cell NADH." (PMID 33919790, 2021). "At functional level, the upregulation of LDHA by POU1F1 interferes with mitochondrial respiration, turning cancer cell metabolism into aerobic glycolysis instead of OXPHOS." (PMID 33714987, 2021). "Since then, many studies have demonstrated elevated levels of LDHA, MCTs and pyruvate dehydrogenase kinase 1 (PDK1) (which inactivates PDH), which are considered hallmarks of cancer cells." (PMID 31936895, 2020). "Lactate dehydrogenase A (LDHA) is an enzyme that converts pyruvate to lactate, and its overexpression is also observed in many types of cancers." (PMID 33123488, 2020). "Accordingly, inhibition of LDHA activity compromised the tumorigenesis and proliferation of HER-2 initiated cancer cells." (PMID 33173435, 2020). "The highest glycolysis score, LDHA and PGK1 mRNA abundance were observed under high hypoxia and high P4HA1 expression in some cancer types." (PMID 32635458, 2020). "GPC1-subtype tumors displayed distinct Warburg-like proteomic features, with increased LDHA, PKM2, and HK2 expression that facilitates lactate production and confers resistance to hypoxic stress in cancer cells." (PMID 32620753, 2020). "We show that higher lactate concentration in cancer tissue is concomitant with a shift in isozyme pattern towards the “muscle-type” LDH and corresponding LDHA and LDHB protein expression changes." (PMID 33353120, 2020). "The glycolysis of cancer cells is catalyzed by several key regulators, including glucose transporter 1 (GLUT1), lactate dehydrogenase A (LDHA) and hypoxia-inducible factor 1α (HIF1α)." (PMID 32863913, 2020). "It has been well documented that LDHA and PKM2 are overexpressed in a number of cancers and play pivotal roles in the Warburg effects." (PMID 32572027, 2020). "Various cancer cells with high CK2 kinase activity showed Glc requirement and increased endogenous LDHA expression." (PMID 30926903, 2019). "Based on these points of view, we suppose that the novel LDHA inhibitor, PSTMB, can be a potent candidate for development of anti-cancer therapeutic agents." (PMID 30850682, 2019). "Recent studies have shown that suppression of aerobic glycolysis by LDHA inhibitors, including FX11 and oxamate, impaired the progression of cancer through induction of oxidative stress." (PMID 30850682, 2019). "We found cMyc decreases pyruvate levels by promoting LDHA and PKM2 levels, this can consequently decrease the inhibition to HDAC3 and protect cancer cells from apoptosis." (PMID 30866966, 2019). "Matrine inhibits the mRNA and protein expression of HIF-1α, thereby suppressing the transcription of GLUT1, HK2, and LDHA, the downstream targets of HIF-1, which are the key enzymes involved in the glycolytic energy metabolism of cancer cells." (PMID 31849679, 2019). "Accumulating intracellular lactate moves LDHA catalyzed-reaction to produce pyruvate, which prevents NAD+ regeneration and affects the energy source that established a fine competition between cancer cells that resulted in cell death." (PMID 31921661, 2019). "The simultaneous co-inhibition of LDHA and HK2 can induce the death of cancer cells that depend upon glycolysis." (PMID 31483850, 2019). "Furthermore, MA markedly decreased LDHA activity, lactate production, and intracellular adenosine triphosphate (ATP) levels induced by hypoxia-induced LDHA expression in cancer cells, and significantly inhibited colony formation, leading to reduced cancer cell survival." (PMID 31324019, 2019).